ZSCAN5A (zinc finger and SCAN domain containing 5A)
Description:
May be involved in transcriptional regulation.
Synonyms: ZNF495; ZSCAN5; MGC4161
Tractability: PROTAC: UniProt records ubiquitination sites on it.
Gene: Protein-coding gene on chromosome 19 (56,219,670 to 56,368,383, reverse strand). Ensembl gene ENSG00000131848.
Subcellular location: Nucleus
Subcellular location (Human Protein Atlas): Nuclear speckles
Gene Ontology:
Molecular function: protein binding; sequence-specific double-stranded DNA binding; DNA-binding transcription factor activity, RNA polymerase II-specific; RNA polymerase II cis-regulatory region sequence-specific DNA binding
Biological process: regulation of transcription by RNA polymerase II
Cellular component: nucleus
Genetic constraint (gnomAD): Loss-of-function variants: 12 observed, 23.2 expected, observed/expected ratio (o/e) 0.52, 90% interval 0.33 to 0.84. The upper end of that interval is the gene's LOEUF score, 0.84, which puts it in group 3 of 6, group 1 being the genes least tolerant of losing a copy. Missense variants: 597 observed, 619.9 expected, observed/expected ratio (o/e) 0.96, 90% interval 0.9 to 1.03. Synonymous variants: 257 observed, 241.65 expected, observed/expected ratio (o/e) 1.06, 90% interval 0.96 to 1.18.
Homologues: Orthologues: chimpanzee ZSCAN5A (99% identical), macaque ZSCAN5A (93% identical), rat Zscan5b (35% identical), mouse Zscan5b (35% identical), Drosophila melanogaster CG12391 (15% identical), zebrafish ovol1a (12% identical), zebrafish plagl2 (11% identical), Drosophila melanogaster hb (11% identical), zebrafish ovol1b (10% identical), Caenorhabditis elegans lin-48 (9% identical), zebrafish plagx (9% identical), Caenorhabditis elegans hbl-1 (8% identical), and 1 more. Paralogues in human: ZSCAN5C (84% identical), ZSCAN5B (79% identical), ZKSCAN2 (25% identical), ZSCAN29 (25% identical), ZSCAN32 (25% identical), ZNF18 (24% identical), ZNF202 (23% identical), ZNF174 (23% identical), ZNF274 (23% identical), ZNF496 (22% identical), ZNF444 (17% identical), ZNF446 (17% identical), and 17 more.
Diseases named in the same sentence as ZSCAN5A in open-access papers:
ZSCAN5A is named in the same sentence as 3 diseases in open-access papers, as found by Europe PMC text mining. Sharing a sentence is not in itself a finding about the gene and the disease. The quoted sentences say what the papers report.
diabetic retinopathy (1 paper, 2023). "When investigating sub-phenotypes of T2DM, diabetic retinopathy has been identified to be associated with ACVRIC (rs4664229), ZFHX4 (rs61729527), WNT9B (rs4968281), SHANK3 (rs9616915), ZSCAN5A (rs7252603), and DCP1B (rs715146, rs1044950, rs113147414) gene." (PMID 37033211, 2023).
infection (2 papers, 2023 to 2025). The state of being infected such as from the introduction of a foreign agent such as serum, vaccine, antigenic substance or organism. "Western Blot as well as qRT-PCR experiments further confirmed the expression of DUX4 and known DUX4-target genes TRIM48, TRIM49, ZSCAN4, ZSCAN5a, ZSCAN5d and RFPL4A upon HSV-1, HCMV and KSHV-infection 25 in different experimental settings." (PMID 38168299, 2023).
cancer (1 paper, 2021). A tumor composed of atypical neoplastic, often pleomorphic cells that invade other tissues. "MGAT4C, HSPA4L, ZSCAN5A, LOC100505841, and NALCN gene deletions were associated with cancer patients without FCH (p < 0.05), while SMYD3 and NKD2DSV genes were associated with cancer patients with FCH (p < 0.05)." (PMID 33431054, 2021).